CRP (C-reactive protein)
Diseases named in the same sentence as CRP in open-access papers (continued):
Sharing a sentence is not in itself a finding about the gene and the disease.
bacteremia (continued). "Although LDH, CRP, uses of oxygen and vasopressors, and qSOFA, were also prognostic factors for non-survivors of LM bacteremia, in those with higher scores of MEDS (≥10) and NEWS (≥8), we recommended an early goal-directed therapy and appropriate antibiotics as early as possible to reduce mortality." (PMID 34827066, 2021). "Although the average values of CRP on the first day were higher for the bacteremia group than patients with localized infection, it is a non-specific marker to distinguish the cause of febrile neutropenia and to predict fever complication at the onset of the injury within the first 24 hours." (PMID 34324506, 2021). "All of these findings are in favor of a greater value of PCT to distinguish bacteremia from nonbacteremia, which might be due to increased production of CRP in cancer, especially hematologic malignancies." (PMID 33178372, 2020). "In febrile neutropenia, only PCT discriminated bacteremia from non-bacterial infection (AUC: 0.624) whereas CRP could not detect bacteremia (AUC: 0.500, 95% CI: 0.439–0.561, P > 0.05)." (PMID 31821331, 2019). "However several studies have shown that PCT and CRP are not sensitive and/or specific enough to diagnose bacteremia or to differentiate it from other systemic inflammatory responses." (PMID 29596458, 2018). "While the performance of CRP and PCT is generally similar, there is some evidence that PCT may be more accurate than CRP for detecting invasive bacterial infections (IBI, defined as bacteremia and meningitis) in children <3 months of age." (PMID 28862659, 2017). "Similarly, another study with 78 patients showed that endocan plasma levels at day 0 are in patients with bacteremia compared to those without bacteremia, but neither CRP levels nor PCT levels at day 0 are different between the two groups." (PMID 27699168, 2016). "However, some neonates with bacteremia have a CRP level within the normal range and they are not well characterized." (PMID 26259626, 2015). "The authors observed that only the CRP level at the onset of fever could discriminate patients with or without bacteremia." (PMID 24286072, 2013). "We speculate that this occurred because of the rise in CRP reactivity rather than because of the bacteremia itself." (PMID 22809118, 2012). "Interestingly, CRP levels were significantly higher in the blood culture-negative group than in the bacteremia group (P = 0.033)." (PMID 22809118, 2012). "However, other laboratory values that might routinely be measured in patients presenting with febrile UTI such as C-reactive protein (CRP) and the erythrocyte sedimentation rate (ESR) could also be indicative for the presence of bacteremia." (PMID 21083886, 2010). "In the random forest analysis, whether comparing the CRP levels measured 12-24 hours after birth with those measured immediately after birth or including other factors such as WBC counts and PROM, the late CRP consistently emerged as the most important predictor of bacteremia." (PMID 40809608, 2025). "However, the bacteremia-negative cohort exhibited surprisingly high CRP levels." (PMID 39467995, 2024). "The bacteremia group had a higher body temperature (BT) at triage, especially in neonates, higher pulse rates at triage, longer fever subsidence time, longer hospital stays, higher neutrophil counts, and higher C-reactive protein (CRP) levels than those of the non-bacteremia group." (PMID 37679686, 2023). "Further studies showed that repeatedly negative CRP (<10 mg/L) results after 24–48 h exclude an infection with high certainty, while on the other hand, it has been estimated that a bacteremia can be proven by bacteriological cultures in 10% of symptomatic neonates." (PMID 36233706, 2022). "However, in 273 febrile neutropenia, only PCT discriminated bacteremia from non-bacterial infection (AUC: 0.624, 95% CI: 0.564–0.682) whereas CRP could not detect bacteremia (AUC: 0.500, 95% CI: 0.439–0.561, P > 0.05)." (PMID 31821331, 2019).
bacteremia (continued). "Subgroup analysis excluding patients with septic arthritis without concurrent bacteremia, and likewise exclusion of the patients with septic arthritis caused by coagulase negative staphylococci, both improved the diagnostic accuracy of CD64 and PCT, but not of WBC and CRP." (PMID 23783182, 2013). "However, no studies have reported whether sTREM-1, PCT, or CRP levels are good parameters for the prognosis of bacteremia." (PMID 22809118, 2012). "Unlike IL-6, CRP, and PCT, sNRP-1 showed stable elevated levels in the bacterial sepsis group throughout the 7-day observation period." (PMID 40733612, 2025). "Compared to conventional infection markers such as IL-6, CRP, and WBC, NLR exhibits a high degree of sensitivity, specificity, and positive rate for bacteremia and is not affected by the type of transplanted organ or the patient’s sex." (PMID 40276743, 2025). "Since the use of the qPitt bacteremia score in Gram-negative BSI is limited and its relationship with CRP/albumin ratio in patients with BSI is largely unexamined, we sought to explore this further." (PMID 39252713, 2024). "PCT was more accurate than CRP to predict bacteremia, for discriminating bacterial from nonbacterial infections, and for determining bacterial species (i.e., AUC of PCT and CRP were 0.79 and 0.66, respectively)." (PMID 37296721, 2023). "In conclusion, this study has demonstrated that it is not possible to predict bacteremia in neonates using ML models based on CBC and CRP." (PMID 36502550, 2023). "The first article, by reporting elevated biomarkers of inflammation (CRP, PCT, cytokines) and pyrexia in patients without bacteremia provides indirect proof of endotoxemia (as endotoxin was not directly measured)." (PMID 37048662, 2023). "Regardless of the occurrence of bacteremia or fungemia, the CRP, PCT, and IL-6 levels showed significant differences on each day of hospitalization, and this discrepancy was larger in the absence of bacteremia." (PMID 36555941, 2022). "Comparison on serum CRP, PCT and cytokine levels of bacterial respiratory infectious NHL patients with or without bacteremia." (PMID 35463642, 2022). "The ROC curve analysis for predicting culture-proven bacterial infection with or without bacteremia yielded an AUC value 0.596 (95% CI: 0.551–0.641) for presepsin, 0.665 (95% CI: 0.621–0.709) for PCT, and 0.581 (95% CI: 0.550–0.642) for CRP." (PMID 36072944, 2022). "Cut-off concentrations of 5 mg/ml for CRP and 350 pg/mL for PSEP were not useful for discriminating between candidemia and bacterial sepsis because the serum concentrations of these markers exceeded these cut-offs in all patients in both groups." (PMID 35330311, 2022). "Despite physicians’ judicious and careful selection of cases in current practice, while most of the cases are tested with CRP, PCT tests and BCs do not indicate bacteremia." (PMID 35351003, 2022). "In this study, we evaluated the value of CRP marker and PCT in differentiating bacteremia from nonbacteremia as well as differentiating bacteremia from contamination in peripheral blood cultures." (PMID 33178372, 2020). "ROC curves were generated for CRP and PCT levels to detect bacteremia in a total of 614 febrile episodes, in non-neutropenic febrile episodes, and in neutropenic febrile episodes." (PMID 31821331, 2019). "When comparing neonates with and without bacteremia, factors such as gestational age, birth weight, WBC count, platelet count, antibiotic use, and CRP levels (first and second) were analyzed, as well as maternal factors such as WBC count, platelet count, and PROM ≧18 hours." (PMID 40809608, 2025). "Physician characteristics of race, gender and immigration status impacted whether to include a CRP as part of a LOS evaluation but otherwise did not influence LOS evaluation, including the likelihood of bacteremia." (PMID 38667607, 2024).
bacteremia (continued). "Thus, it is not that biomarkers are not useful to predict bacteremia; rather, CBC and CRP are the incorrect biomarkers for this purpose." (PMID 36502550, 2023). "The patient appeared acute gouty arthritis as previous, with fever and elevated WBC, CRP and PCT, but the puncture induced bacteremia could not be ruled out." (PMID 38134096, 2023). "No steady decrease in CRP, PCT, and IL-6 levels was observed in the absence of bacteremia." (PMID 36555941, 2022). "Also, in comparison between bacteremia and nonbacteremia, the AUC of PCT was higher than CRP, and the P value of PCT as a single test was statistically significant, but it is not for CRP." (PMID 33178372, 2020). "From these results, when the endocan level is high in patients, even if CRP and PCT levels are not high at the onset of the infection, the presence of bacteremia might be predicted." (PMID 25894539, 2015). "Our study implies that sTREM-1, CRP, and PCT levels may possess no clinical value in determining whether a given septic patient is complicated with bacteremia on the grounds of a new fever." (PMID 22809118, 2012). "This is like other studies that did not recommend the use of CRP and ESR for diagnosing bacteremia." (PMID 21083886, 2010). "In accordance to earlier reports, by combining CRP and WCC measurements we could not further improve specificity for the diagnosis of bacteremia." (PMID 17868441, 2007). "Therefore, recent interest has focused on inflammatory biomarkers for early assessment of bacterial sepsis, including procalcitonin (PCT) and C-reactive protein (CRP), however, these biomarkers could be elevated in non-infectious conditions." (PMID 36072944, 2022).
breast cancer (339 papers, 2004 to 2026). A primary or metastatic malignant neoplasm involving the breast. "Among the commonly studied inflammatory markers, CRP serves as a general indicator of systemic inflammation and has been associated with increased breast cancer risk, disease progression, and poorer survival outcomes." (PMID 40901118, 2025). "For example, high levels of C-reactive protein were significantly associated with worse prognosis in patients with breast cancer." (PMID 40510180, 2025). "Specifically, inflammation markers such as monocyte count, neutrophil count, and C-reactive protein were linked to an increased risk of postmenopausal breast cancer." (PMID 39609539, 2025). "Elevated CRP levels, a well-established marker of systemic inflammation, have been linked to an increased risk of breast cancer development." (PMID 40901118, 2025). "Elevated CRP levels have been associated with poor prognosis in breast cancer, indicating higher tumor burden, lymph node involvement, and metastatic disease." (PMID 40486605, 2025). "Elevated levels of testosterone and C-reactive protein (CRP) have been associated with an increased risk of breast cancer, whereas higher levels of sex hormone-binding globulin (SHBG) correlate with a reduced risk." (PMID 39791640, 2024). "In breast cancer survivors, an aerobic and resistance training program has been associated with a significant serum levels reduction of c-reactive protein (CRP), interleukin (IL)-6, -8, and -10, and tumor necrosis factor (TNF)-α." (PMID 39458125, 2024). "The association between CRP and breast cancer has been reported in previous studies, and further confirmed by a recent Mendelian randomization analysis." (PMID 38360584, 2024). "The inverse association between HLI and breast cancer was weakly mediated by CRP (8.5%), SII (1.71%), CAR (8.66%), CLR (6.91%), MHR (6.27%), and NHR (7.33%)." (PMID 38360584, 2024). "In another longitudinal sample from the Health, Eating, Activity, and Lifestyle (HEAL) prospective cohort study, higher postdiagnosis HEI-2015 scores were associated with lower CRP levels in breast cancer survivors." (PMID 38532045, 2024). "For instance, elevated levels of testosterone and CRP (C-reactive protein) are linked to increased breast cancer risk, whereas higher levels of SHBG (sex hormone-binding globulin) are associated with reduced risk." (PMID 39791640, 2024). "The association of HLI and breast cancer is weakly mediated by the level of inflammation, particularly by CRP and CAR." (PMID 38360584, 2024). "Meta-analysis suggested that women with the highest levels of C-reactive protein (CRP) had a higher risk of developing breast cancer [risk ratio (RR) = 1.13; 95% confidence interval (CI), 1.01-1.26] compared with women with the lowest levels." (PMID 36867866, 2023). "Two studies found that more severe fatigue is strongly associated with higher concentrations of serum CRP, which can serve as an independent predictor of fatigue severity in patients with breast cancer and multiple myeloma." (PMID 38136423, 2023). "•Serum CRP was more likely to be associated with invasive breast cancer and its transition to death from breast cancer." (PMID 38000092, 2023). "Apart from the associations with overall reduced physical health, significant associations were found for elevated plasma C-reactive protein and glycosylated hemoglobin HbA1c levels in breast cancer survivors." (PMID 37513516, 2023). "Three key inflammatory biomarkers associated with inflammation in breast cancer survivors are CRP, IL-6, and IL-18." (PMID 36717689, 2023). "Eleven hematological and biochemical markers were found to be associated with breast cancer risk, among which higher serum levels of CRP, testosterone, and IGF-1 were also associated with a higher breast cancer mortality." (PMID 38000092, 2023). "Our results only found the association between PhA and oxidant, antioxidant, CRP, and AL in the breast cancer group." (PMID 37289671, 2023).
breast cancer (continued). "Studies have shown that systemic inflammation – characterized by elevated levels of TNF-α, IL-6 and CRP – is associated with an increased risk of breast cancer progression and death." (PMID 36482346, 2022). "For example, elevated plasma levels of C-reactive protein are associated with reduced disease-free survival of breast cancer patients." (PMID 35795310, 2022). "In a study consisted of 700 women with early-stage breast cancer found that elevated levels of CRP measured 2.5 years after diagnosis were associated with reduced DFS and OS." (PMID 35924148, 2022). "Obesity, insulin resistance, dyslipidemia, leukocytosis, and elevated C-reactive protein are associated with reduced gut microbial diversity, some of which are associated with breast cancer." (PMID 36419880, 2022). "Two meta-analyses of such studies found associations between serum C-reactive protein (CRP) and incidence of breast cancer." (PMID 35406394, 2022). "Genetically predicted higher CRP levels were associated with a lower risk of schizophrenia with consistent results across sensitivity analyses and breast cancer." (PMID 36376304, 2022). "Many prospective studies have examined the relation between higher blood levels of c-reactive protein (CRP), and risk of breast cancer, and the overall findings indicate a modest positive association." (PMID 36153518, 2022). "A positive association of genetically elevated CRP levels on breast cancer was identified with IVW (β = 0.061, p = 3.56 × 10−3), with concordant direction of effect across MR methods." (PMID 35459240, 2022). "Recent studies have suggested that increased pretreatment with CRP concentrations has been linked to a higher recurrence and poorer survival in women with breast cancer." (PMID 35159065, 2022). "The most studied inflammatory biomarker within the framework of breast cancer risk is C-reactive protein (CRP), a marker of the acute-phase inflammatory response." (PMID 35430795, 2022). "Previous studies revealed that increased CRP levels are associated with an increased risk of breast cancer." (PMID 36467500, 2022). "In the most recent meta-analysis of twelve prospective studies on CRP-breast cancer associations, a doubling of CRP levels was associated with a 7% higher risk of breast cancer." (PMID 35430795, 2022). "As In ours, some studies observed a strong attenuation of the associations between CRP and leptin and postmenopausal breast cancer risk after adjustment for BMI suggesting that BMI was a confounder in the inflammation-breast cancer association." (PMID 35430795, 2022). "This study aimed to investigate level fluctuations of serum biomarkers that are associated with cardiotoxicity risk, such as high-sensitivity C-reactive protein (hs-CRP) and apolipoprotein-B (Apo-B) in response to chemotherapy treatment for breast cancer." (PMID 34711013, 2021). "Because of inconsistencies across studies, further research should be performed to confirm the positive association between blood CRP levels and breast cancer risk." (PMID 33435254, 2021). "Obesity is an important risk factor for breast cancer, and plasma CRP levels are elevated in 7.7% and 20.2% of overweight and obese middle-aged women, respectively, compared with 4.8% in normal weight women." (PMID 34359821, 2021). "Previous studies revealed that elevated plasma CRP levels were associated with increased risk of breast cancer, lung cancer, prostate cancer and colorectal cancer 29-31." (PMID 33613752, 2021). "They observed a reduction in inflammation and pain associated with a reduction in CRP in breast cancer patients with aromatase-induced musculoskeletal symptoms (NCT01819948)." (PMID 33572626, 2021). "Chronic inflammation and high CRP levels are associated with poor survival of several types of cancer, including renal cell, lung, pancreatic, and breast cancer." (PMID 33562331, 2021).